ENSG00000278775
Gene: Miscellaneous RNA gene on chromosome 21 (8,433,085 to 8,433,174, forward strand). Ensembl gene ENSG00000278775.
Gene Ontology:
Biological process: chromatin remodeling